RNU4-36P (RNA, U4 small nuclear 36, pseudogene)
Gene: Small nuclear RNA gene on chromosome 16 (68,535,515 to 68,535,658, forward strand). Ensembl gene ENSG00000201164.
Homologues: Orthologues: chimpanzee U4 (98% identical), macaque U4 (92% identical). Paralogues in human: RNU4-49P (82% identical), RNU4-50P (75% identical), RNU4-81P (75% identical), RNU4-90P (71% identical), RNU4-15P (67% identical), RNU4-40P (64% identical), RNU4-28P (63% identical), RNU4-52P (63% identical), RNU4-10P (62% identical), RNU4-66P (62% identical), RNU4-24P (62% identical), RNU4-51P (62% identical), and 82 more.